TTR (transthyretin)
Diseases named in the same sentence as TTR in open-access papers (continued):
Sharing a sentence is not in itself a finding about the gene and the disease.
amyloidosis (continued). "For example, liver transplantation is not a treatment for wild type ATTR amyloidosis, but is helpful for hereditary ATTR amyloidosis; Tafamidis and other medicines are used to stabilize the tetramer of TTR." (PMID 36120541, 2022). "Consistent with its ATTR selectivity, NI301A did not bind corresponding preparations from cardiac tissues without amyloid deposits (A−) or amyloid deposits unrelated to TTR (A+TTR−)." (PMID 34035264, 2021). "In experimental murine models of amyloidosis in vivo, IDOX specifically accumulated in amyloid deposits of amyloid A, immunoglobulin LC, transthyretin (TTR), amyloid β (Aβ) and β2microglobulin (β2M) but did not bind to the monomeric amyloid precursor." (PMID 31546787, 2019). "Tafamidis, an oral, non-NSAID, highly specific TTR stabilizer has emerged as the new standard of care for ATTRV30M and remains the only medicine approved for the treatment of transthyretin amyloidosis in adult patients with stage 1 symptomatic polyneuropathy." (PMID 30327725, 2018).
cardiac amyloidosis (475 papers, 2008 to 2026). Cardiac amyloidosis is a condition whereby cardiac tissue is infiltrated by amyloid fibrils. "We assembled clinicians, researchers, and patients to participate in a co-design workshop using the first step of System Evaluation Theory to define an ideal testing and diagnostic protocol using transthyretin cardiac amyloidosis as a case study." (PMID 41544075, 2026). "Prognosis depends on the extent of cardiac amyloidosis coupled with factors such as the patient’s age at symptom onset, the time between initial symptoms and diagnosis, and the specific TTR mutation in ATTRv." (PMID 41030053, 2026). "The primary outcome was all-cause mortality, comparing transthyretin cardiac amyloidosis (TTR-CA) patients by ICD status and against matched NICM patients." (PMID 41659101, 2026). "Cardiac amyloidosis is an infiltrative cardiomyopathy caused by extracellular deposition of misfolded proteins, most commonly immunoglobulin light chains (AL) or transthyretin (ATTR), with rarer forms occurring less frequently." (PMID 41681748, 2026). "A key underlying cause of HFpEF is cardiac amyloidosis, an infiltrative disorder characterized by extracellular deposits of misfolded transthyretin protein that impair myocardial structure and function." (PMID 40674251, 2025). "We report a confirmed case of coexistent AL-CA and wild-type transthyretin cardiac amyloidosis, validated through comprehensive diagnostic evaluation." (PMID 41367026, 2025). "Cardiac amyloidosis (CA) is a severe disease caused by amyloid light chain (AL-CA) or transthyretin (ATTR-CA) fibrils that infiltrate cardiac tissue." (PMID 40629395, 2025). "Surprisingly, the p.Val142Ile variant (NM_000371.4:c.424G>A), known to be associated with the TTR-related cardiac amyloidosis, particularly prevalent in persons of African ancestry, was also present in 0.16%." (PMID 40332002, 2025). "Two main precursor proteins are implicated in cardiac amyloidosis: transthyretin (TTR), synthesized by the liver, and immunoglobulin light chain (AL), usually associated with plasma cell dyscrasias and lymphomas." (PMID 41024906, 2025). "Background/Objectives: Transthyretin cardiac amyloidosis (ATTR-CA) is an infiltrative cardiomyopathy caused by transthyretin (TTR) amyloid deposition in the myocardium, increasingly recognized in patients with aortic stenosis (AS)." (PMID 40283481, 2025). "Among the more than 150 known TTR variants, p.Val142Ile is one of the most clinically relevant mutations, particularly due to its association with late-onset cardiac amyloidosis." (PMID 40870008, 2025). "Transgenic mouse models expressing human WT or variant TTR have offered insights into the development of amyloid cardiomyopathy, but challenges persist in fully replicating the human phenotype." (PMID 40889301, 2025). "Although Afro-Caribbean (AC) race has been associated with worse outcomes in many cardiovascular diseases, its potential association with transthyretin cardiac amyloidosis (ATTR-CA) is less understood." (PMID 40474003, 2025). "The diminished probiotics were negatively associated with TTR cardiac amyloidosis through metabolites like GABA and taurine." (PMID 39857728, 2025). "iPSC lines have also been generated from patients with transthyretin amyloid cardiomyopathy with mutations in the transthyretin gene." (PMID 40507801, 2025). "The most prevalent variant is the wild type form of transthyretin cardiac amyloidosis (ATTR-CM), which predominantly affects older adults and leads to progressive cardiac dysfunction and worsening HF symptoms." (PMID 40674251, 2025). "Wild‐type transthyretin amyloid cardiomyopathy (ATTRwt‐CM) is caused by the progressive accumulation of insoluble amyloid fibrils formed by transthyretin (TTR) in the myocardial extracellular space." (PMID 41317156, 2025). "Misfolded amyloid proteins formed from light chain (AL) or transthyretin (ATTR) accumulation in the myocardium cause cardiac amyloidosis (CA)." (PMID 41502999, 2025).
cardiac amyloidosis (continued). "Three of them demonstrated positive imaging findings indicative of transthyretin cardiac amyloidosis (ATTR-CA), meeting the 2020 AHA diagnostic criteria for cardiac amyloidosis with Grade 2–3 radiotracer uptake on visual grading." (PMID 40296002, 2025). "In general, the management approach to a patient with cardiac amyloidosis involves treatment of the underlying cause (chemotherapy for AL, TTR‐directed therapies for ATTR) and concurrent management of heart failure, arrhythmia, and accompanying symptoms." (PMID 39563857, 2024). "Bone scintigraphy is emerging as a confirmatory diagnostic tool for transthyretin cardiac amyloidosis (ATTR-CA)." (PMID 39095877, 2024). "The two subtypes include transthyretin cardiac amyloidosis caused by misfolded transthyretin protein deposition and light-chain amyloidosis caused by abnormal circulating immunoglobulin light-chain deposition." (PMID 39070422, 2024). "Wild-type transthyretin amyloid cardiomyopathy (ATTRwt-CM) is an underrecognized cause of heart failure due to misfolded wild-type transthyretin (TTRwt) myocardial deposition." (PMID 38233673, 2024). "Transthyretin stabilizers such as tafamidis and diflunisal present a novel approach to prevent the misfolding and aggregation of proteins implicated in amyloid cardiomyopathy." (PMID 38329532, 2024). "Cardiac amyloidosis (CA) results mainly from the infiltration of the myocardium by either immunoglobulin light-chain fibrils (AL) or transthyretin fibrils (ATTR), causing restrictive cardiomyopathy and eventually death if untreated." (PMID 39064115, 2024). "Variant transthyretin amyloidosis cardiomyopathy (ATTRv-CM) is a rare form of cardiac amyloidosis associated with many possible mutations in the transthyretin gene, presenting as various distinct clinical phenotypes." (PMID 39768780, 2024). "The TTR Val142Ile variant confers risk for cardiac amyloidosis which typically has clinical onset after the fifth decade as heart failure and arrhythmias." (PMID 38229148, 2024). "TTR protein stabilizing therapy such as Tafamidis in patients with transthyretin cardiac amyloidosis has been shown to increase TTR levels by stabilizing the native tetrameric structure of TTR and decreasing the risk of mortality." (PMID 39043640, 2024). "Transthyretin is a transport protein whose misfolding has been implicated in the development of cardiac amyloidosis." (PMID 39043640, 2024). "In this article, we report a case of a Chinese patient with transthyretin mutation p.D58Y and provide detailed information on cardiac amyloidosis, including transthoracic echocardiography, cardiac magnetic resonance, and SPECT imaging for the first time." (PMID 38841257, 2024). "Cardiac amyloidosis (CA) is an underdiagnosed condition caused by the deposition of misfolded proteins, namely immunoglobulin light chains and transthyretin, in the extracellular spaces of the heart." (PMID 37735319, 2024). "Cardiac amyloidosis (CA) is caused by deposition of misfolded proteins in the myocardium, including transthyretin (ATTR) or immunoglobulin light chains (AL)." (PMID 39763545, 2024). "The hereditary variant of transthyretin cardiac amyloidosis (ATTRv-CA) is an autosomal dominant disease caused by a genetic mutation leading to the destabilization of transthyretin proteins." (PMID 38826962, 2024). "Cardiac amyloidosis is a devastating and progressive infiltrative cardiomyopathy caused by the extracellular deposition of misfolded transthyretin." (PMID 36776255, 2023). "Cardiac amyloidosis has become more recognized with the advent of genetic testing, especially with the TTR c.424G>A (p.Val142Ile) gene variant commonly found in patients with African ancestry." (PMID 37373876, 2023). "This animal model and associated features observed as result of cardiac TTR deposition provide a promising and invaluable research tool for a better understanding of the implicated pathways that lead to the lethality associated to TTR cardiac amyloidosis." (PMID 36968272, 2023).
cardiac amyloidosis (continued). "Cardiac amyloidosis is a disease caused by the deposition of amyloid fibrils in the extracellular space of the heart, most often by immunoglobulin light chains or by transthyretin." (PMID 38249187, 2023). "Cardiac amyloidosis is often implicated in two main subtypes: transthyretin (ATTR) and light chain (AL)." (PMID 37342296, 2023). "We present a case of a Caucasian 65-year-old man with cardiac amyloidosis and the homozygous mutation Val142Ile (classically, Val122Ile) in the transthyretin gene." (PMID 37711552, 2023). "The extracellular deposition of misfolded proteins in organs is responsible for various disorders, such as transthyretin cardiac amyloidosis, a disease causing an infiltrative/restrictive cardiomyopathy." (PMID 36829983, 2023). "Treatments for cardiac amyloidosis include transthyretin stabilizers for patients with TTR cardiac amyloidosis, and early clinical management has been linked with improved outcomes." (PMID 37373876, 2023). "The vast majority of cases of cardiac amyloidosis (CA) are caused by the accumulation of immunoglobulin light-chain (AL–CA) or transthyretin (ATTR–CA), a carrier for thyroxine and retinol-binding protein." (PMID 37341947, 2023). "The most frequent cases of cardiac amyloidosis are caused by transthyretin and light chain amyloidosis." (PMID 37189662, 2023). "There are 2 types of cardiac amyloidosis, hereditary transthyretin cardiac amyloidosis that results from mutations in TTR, and senile transthyretin cardiac amyloidosis, in which WT transthyretin deposits in the myocardium and valves." (PMID 35104251, 2022). "As specific TTR variants that destabilize TTR structures were known to be associated with either amyloid cardiomyopathy or familial amyloid neuropathy, the tafamidis story also highlights the power of human genetics to elucidate viable therapeutic strategies." (PMID 37123434, 2022). "One common form of cardiac amyloidosis is due to deposition of insoluble, misfolded transthyretin (TTR) fibrils due to rare genetic point mutations, and more commonly from aging." (PMID 35262277, 2022). "In cardiac amyloidosis (CA), extracellular deposits of amyloid fibrils originating from circulating immunoglobulin amyloid light chains (AL) or transthyretin proteins (TTR) accumulate and cause extracellular infiltration." (PMID 36290299, 2022). "The present study describes one of the largest series of CIE in Afro-Caribbean cardiac amyloidosis patients presenting with V122I and I107V transthyretin variants." (PMID 35665045, 2022). "In their subsequent work, they found that the stability of TTR(H88R), the known variant associated with amyloid cardiomyopathy, is much less than that of WT; thus, it is more prone to aggregation." (PMID 33922648, 2021). "We derived and validated a machine learning model based on medical diagnostic codes that identifies heart failure patients at risk for wild-type transthyretin amyloid cardiomyopathy." (PMID 33976166, 2021). "In a clinical trial including 120 patients with TTR cardiac amyloidosis demonstrates that an increased survival is associated with diflunisal treatment." (PMID 33679409, 2021). "Certain systemic “red flags”, including carpal tunnel syndrome (CTS) and spinal stenosis (SS), raise clinical suspicion for hATTR and have been found to precede TTR-associated cardiac amyloidosis by 5–10 years." (PMID 33467513, 2021). "The most common types of cardiac amyloidosis (CA) are caused by immunoglobulin-derived light chains (AL) and the precursor protein transthyretin (ATTR)." (PMID 33922892, 2021). "Cardiac amyloidosis was evident in 30% of samples and were all linked to wild-type transthyretin deposition." (PMID 34282465, 2021). "Mutated serum TTR results in familial systemic amyloidosis, whereas wild-type TTR results in senile cardiac amyloidosis predominantly seen in elderly males." (PMID 34040908, 2021).
cardiac amyloidosis (continued). "Wild‐type transthyretin cardiac amyloidosis (ATTRwt) is now recognized as a common cause of heart failure with preserved ejection fraction (HFpEF)." (PMID 31825134, 2020). "Recent evidence suggests cardiac amyloidosis (CA) is a mostly underdiagnosed condition, particularly in the transthyretin-mediated form, and is a frequent cause of heart failure with preserved ejection fraction (HFpEF) in the elderly." (PMID 33295462, 2020). "Transthyretin amyloid cardiomyopathy is caused by the deposition of wild-type (liver transplant not useful in this case) or variant transthyretin amyloid fibrils in the myocardium." (PMID 31117178, 2019). "Cardiac amyloidosis is also associated with mutant and wild-type forms of transthyretin (Amyloid Transthyretin Amyloidosis or ATTR)." (PMID 31452023, 2019). "This is the first case of hereditary cardiac amyloidosis associated with a TTR mutation (Pro24Ser) in Japan." (PMID 30553273, 2018). "Here we report the case of a patient with hereditary cardiac amyloidosis associated with a Pro24Ser mutation in transthyretin, which is the first case reported in Japan." (PMID 30553273, 2018). "We report a case of isolated cardiac amyloidosis associated with a Pro24Ser mutation in TTR, which is the first case reported in Japan." (PMID 30553273, 2018). "The vast majority of cardiac amyloidosis (CA) is caused by one of two proteins: light chain or transthyretin (TTR)." (PMID 32477799, 2018). "In this report, we described the first case of hereditary cardiac amyloidosis associated with a Pro24Ser TTR mutation in Japan." (PMID 30553273, 2018). "Here we report the case of a patient with cardiac amyloidosis associated with a single mutation in TTR, which is the first case in Japan." (PMID 30553273, 2018). "In this study, 10 controls, 10 heart failure patients, 13 TTR mutation patients and 11 senile cardiac amyloidosis patients were included." (PMID 30332417, 2018). "The non-invasive method canbe used from the use of the Tc99m radiotracer, which binds to TTR but not to thelight chain derivatives, being an effective method of evaluating the mutant orwild forms of cardiac amyloidosis associated with TTR." (PMID 28678923, 2017). "Our approach is unique in that it compares directly two soluble TTR variants with extremely different amyloidogenic and cytotoxic potential on cells that are relevant to TTR cardiac amyloidosis." (PMID 25395306, 2015). "In contrast, V122I TTR, the most prevalent TTR variant causing cardiac amyloidosis and with its clinical role currently under extensive investigation, has stability and susceptibility to cleavage intermediate between S52P and wild-type TTR." (PMID 26286619, 2015). "At least nine precursor proteins have been implicated in the development of cardiac amyloidosis, most commonly caused by multiple myeloma light chain disease and disease-causing mutant or wildtype transthyretin (TTR)." (PMID 26664897, 2015). "There are two major types of proteins often associated with cardiac amyloidosis – monoclonal immunoglobulin light change (AL) and transthyretin (ATTR) which could be a wild-type (often associated with aging) or due to a genetic mutation (variant)." (PMID 41544075, 2026). "However, cardiac amyloidosis is predominantly associated with two main precursor proteins: immunoglobulin light chain (AL) and transthyretin (TTR) amyloid." (PMID 41024906, 2025). "However, cardiac amyloidosis is predominantly linked to two main precursor proteins: transthyretin (TTR) and immunoglobulin light chain (AL)." (PMID 41024906, 2025). "SERPINA1 reduces the risk of cardiac amyloidosis by inhibiting plasmin-mediated transthyretin hydrolysis and aggregation; it modulates the Eph receptor B2 signaling pathway to improve energy metabolism and glucose homeostasis, thereby influencing cardiometabolic diseases." (PMID 41287052, 2025).